TNF (tumor necrosis factor)
Diseases named in the same sentence as TNF in open-access papers (continued):
Sharing a sentence is not in itself a finding about the gene and the disease.
Crohn disease (continued). "Clinical studies have suggested that anti-TNFα treatment in patients with Crohn’s disease does not prevent fibrostenosis but rather promotes ECM deposition, result in resolution of fistulae." (PMID 32528066, 2020). "Anti-TNFα-treatment is frequently used for treating patients suffering from UC and Crohn's disease (CD), but a potential role of TNFα outside of the context of the immune system is still not fully understood." (PMID 31387973, 2019). "Interestingly, RA and Crohn’s disease are Th1 cell-dominant diseases, and TNFI promotes the Th2 cytokine-dominant balance via inhibition of TNF-α." (PMID 31905985, 2019). "In this study, we aimed to identify gene expression changes in inflamed mucosa from Crohn's disease and ulcerative colitis patients treated with 5‐aminosalicylic acid (5‐ASA) (N = 25) or anti‐TNF agents (N = 12) compared to drug‐free IBD patients (N = 12) and non‐IBD control subjects (N = 18)." (PMID 31322753, 2019). "In fact, it was observed that GA C1, one of the most important bioactive compounds present in this mushroom, is able to decrease tumor necrosis factor (TNF)-α, interferon (IFN)-γ, and IL-17A secretion in inflamed colonic cells derived from patients affected by Crohn's disease." (PMID 29872510, 2018). "By the simulation of TNFα or MACR knockout (simulating Granulocyte and Monocyte Apheresis), a decrease in MMPs node was observed, which is in line with therapy success in clinical practice by a decrease in Crohn's Disease Activity Index (CDAI) Score." (PMID 29513758, 2018). "Besides asthma, GAC1 also activates macrophages and decreases the secretion of inflammatory cytokines including TNF-α, IFN-γ, and IL-17α in PBMNCs and a colonic biopsy of patients with Crohn’s disease." (PMID 29344411, 2017). "Characteristics of 507 patients with Crohn’s disease and poor prognostic factors, who were not affected by intestinal surgery and/or intestinal complications before starting anti-TNF/IM treatment." (PMID 28542298, 2017). "In this pilot study, we included 11 IBD patients (8 Crohn’s disease, 3 ulcerative colitis) previously non-respondent to anti-tumor necrosis factor (TNF)-agents." (PMID 28829369, 2017). "Besides, previous studies revealed that TNF-α blockade treatment decreased CD154 expression in ankylosing spondylitis and Crohn disease." (PMID 28837666, 2017). "Hypoxia significantly reduces tumor necrosis factor α, interleukin (IL)-6 and NLRP3 expression, and increases the turnover of the autophagy protein p62 in colon biopsies of Crohn’s disease patients, and in samples from dextran sulfate sodium-treated mice and Il-10−/− mice." (PMID 28740109, 2017). "The novel effector cells and target cells expressing noncleavable membrane-bound TNFα have been used to quantify ADCC activity in serum from patients with Crohn's disease treated with infliximab and to relate ADCC activity to drug levels." (PMID 29104875, 2017). "Since opportunistic infections were carefully excluded, his paradoxical inflammations were not severe and he wanted to continue anti-TNF-α therapy for his refractory Crohn’s disease, IFX (10 mg/kg for every 8 weeks) was continued cautiously." (PMID 26864464, 2016). "These days, certolizumab and golimumab are the newer, less studied anti-TNF-α antibodies most recently approved by the FDA for the treatment of RA, psoriatic arthritis, ankylosing spondylitis, Crohn's disease unresponsive to regular medications (certolizumab), and ulcerative colitis (golimumab)." (PMID 28083070, 2016). "TNF-α is one of the key cytokines in the formation of non-caseating epithelioid cell granulomas in both sarcoidosis and Crohn’s disease." (PMID 26864464, 2016). "The active Crohn’s disease patients (ac-food, ac-EN and ac-DF) showed a significantly higher level of TNF-α and a non-significantly higher level of IL-6 than that of the Crohn’s disease patients in remission (re-EN and re-DF) and colon cancer patients (can)." (PMID 26140540, 2015).
Crohn disease (continued). "TNF-α blockers, such as infliximab, adalimumab and etanercept, are currently approved by the FDA for the treatment of chronic inflammatory diseases such as RA, Crohn’s disease and ankylosing spondylitis." (PMID 26156520, 2015). "Patients with Crohn’s disease who are over 18 years of age, with newly diagnosed or recurrent active high perianal fistulas, with one internal opening and no anti-TNF usage in the past three months will be considered." (PMID 26289163, 2015). "All anti-TNF-α agents are effective against RA, though with very different efficacies, and not all of them are effective against Crohn’s disease." (PMID 24896264, 2014). "To test this hypothesis, we decided to challenge EGC cultures with TNF-α and IFN-γ, two major apoptosis related cytokines whith key functions in Crohn's disease." (PMID 22251670, 2012). "In contrast, ETN binds mainly soluble TNF-α; the ability of IFX to bind tmTNF-α may explain why IFX but not ETN induces the apoptosis of monocytes and T lymphocytes in Crohn disease." (PMID 22192852, 2011). "The early use of biological therapies, in particular anti-TNF therapies (e.g. infliximab and adalimumab) can induce and significantly increase remission rates without the need for corticosteroids and surgery in Crohn's disease." (PMID 20064220, 2010). "However, unlike in Crohn’s disease, the clinical situations in which anti-TNF therapy can be used as a first-line treatment for ulcerative colitis have not yet been clearly determined." (PMID 41597331, 2025). "Treatment for HPS-related IBD resembles those for Crohn’s disease and ulcerative colitis, but responses to therapy are variable in patients with HPS, many of whom presented poor clinical response to corticosteroids and had to be treated with anti-TNF alpha biologic drugs." (PMID 40176789, 2025). "This may be due to the fact that, in Crohn’s disease, the soluble form of TNFα is not necessarily clinically relevant." (PMID 41470167, 2025). "In the case described, a link between IgA vasculitis and Crohn’s disease or treatment with TNFα inhibitors could not be ruled out." (PMID 38739223, 2024). "Half of the included patients with Crohn’s disease did not use medication, but the other half used thiopurines, anti-TNF, 5-ASA, and/or steroids which could have made our results more heterogeneous." (PMID 37565620, 2023). "Interestingly, in active Crohn’s disease, it was observed that the infliximab (anti-TNF) treatment could modulate the levels IFABP2 and TNF-α and achieve remission." (PMID 36768285, 2023). "However, most genomic markers for anti-TNF response in Crohn’s disease do not reach sufficient thresholds and, therefore, no reproducibility between genetic and expression data exists." (PMID 36145641, 2022). "Furthermore, MALT1 was positively related to C‐reactive protein (CRP), TNF‐α, IL‐17A, and mayo score in A‐UC patients; positively correlated with CRP, erythrocyte sedimentation rate, TNF‐α, and Crohn's disease activity index score in A‐CD patients." (PMID 34997981, 2022). "Monoclonal antibodies against tumor necrosis factor alpha (TNFα), such as infliximab (IFX) or adalimumab (ADA), are safe and effective in induction and maintenance of remission in moderate to severe pediatric Crohn’s disease (CD) and ulcerative colitis (UC) patients." (PMID 34279480, 2021). "Ustekinumab was found to be effective in a phase 2a study conducted in patients with moderate-to-severe Crohn’s disease, and a randomized, double-blind phase 2b study showed an increased response rate in patients with moderate-to-severe Crohn’s disease in whom anti-TNF therapy was not effective." (PMID 34071276, 2021). "Hence, we presumed that TNFα-mediated ERK activation might contribute to ENaC dysfunction in C. concisus infection, as previously demonstrated for Crohn’s disease and lymphocytic colitis." (PMID 31936044, 2020).
Crohn disease (continued). "Biologicals such as anti-tumor necrosis factor (TNF) antibody (infliximab, adalimumab, certolizumab), anti-IL-12/23 (ustekinumab), and anti-α4β7 integrin antibody (vedolizumab) have been approved for Crohn's disease targeting the Th1/Th17-mediated inflammation." (PMID 33415035, 2020). "Recent clinical trial reports have demonstrated that RHB-104 has shown a consequential improvement in CD biomarkers of inflammation such as C-reactive protein (CRP) and Crohn’s disease activity index (CDAI) with or without concomitant anti-TNF-α or immunosuppressive therapy." (PMID 33217961, 2020). "Furthermore, IL-19 suppressed the production of TNFα by PBMCs from healthy patients but not by PBMCs from Crohn’s disease patients." (PMID 29967613, 2018). "JKAP expression was decreased in inflamed mucosa of active IBD patients and was negatively correlated with disease activity [Crohn’s disease activity index (CDAI), Mayo index, C-reactive protein, and erythrocyte sedimentation rate], interleukin-17, and tumor necrosis factor (TNF)-α levels." (PMID 28725226, 2017). "Thus, novel effector cells and target cells expressing noncleavable membrane-bound TNFα have been used to quantify ADCC activity in serum from patients with Crohn's disease treated with infliximab and to relate ADCC activity to drug levels." (PMID 29104875, 2017). "In contrast to Crohn's disease, inflammation in UC has not been thought to be driven by TNFα." (PMID 27491073, 2016). "Like in RA, in spite of the clinical efficacy of anti-TNF treatment, about 50 % of patients with Crohn’s disease do not respond to adalimumab, as determined by lack of a 100-point reduction of the clinical activity score (Crohn’s disease activity index) within 4 weeks after therapy initiation." (PMID 26477946, 2015). "Together with other cytokines, TNF-α holds a central position within immune cell activation and tissue destruction, and the application of TNF-α-antibodies and other antagonistic molecules is a novel therapeutic strategy in the treatment of colitis ulcerosa and/or Crohn's disease." (PMID 22427801, 2012). "Mirtazapine is not recommended, because of the related TNF increase, amitriptyline does not appear to be effective, whereas data on paroxetine are controversial (one study reported an activation of Crohn’s disease after paroxetine treatment)." (PMID 23204981, 2012). "However, infliximab (IFX), a chimeric monoclonal antibody against tumor necrosis factor-alpha (TNF-α), remains the drug of choice in acute severe ulcerative colitis (UC) and the preferable first-line choice in biologic naïve patients with moderate to severe UC or Crohn's disease (CD)." (PMID 39867090, 2024). "Moreover, we found that AD and Crohn's disease (CD) have a similar pattern of expression of basic fibroblast growth factor (bFGF), syndecan 1 (SD1), and tumor necrosis factor α (TNF α), supporting the hypothesis that inflammation may also activate the fibrosis process." (PMID 31001067, 2019). "Five patients (0.6% of the overall patients; n = 3 (60%) Crohn’s disease; n = 2 (40%), ulcerative colitis) were identified as having leukocytoclastic vasculitis (LCV) due to anti-TNF therapy; these patients were white, female, and non-smokers." (PMID 37176606, 2023). "As an anti-tumor necrosis factor (TNF) agent, Infliximab (IFX) is widely used in the treatment of Crohn’s disease, while the adherence is not high." (PMID 37645443, 2023). "Moreover, identified genes aid in better understanding intersections in common molecular pathways of anti-TNF treatment response, and thus may help to discover novel molecular targets for the treatment of Crohn’s disease patients, particularly those who are non-responsive to anti-TNF treatment." (PMID 36145641, 2022). "Because pentoxifylline, acting on TNF-α and IL-1β, is a non-selective PDE inhibitor, PDE activities were investigated in the human normal mucosa and inflamed mucosa of patients with Crohn’s disease." (PMID 36142518, 2022).
Crohn disease (continued). "Golimumab is a fully human monoclonal antibody against tumor necrosis factor (TNF) approved for the treatment of ulcerative colitis and not for Crohn disease (CD)." (PMID 33761677, 2021). "Another TNFα blocking agent is the chimeric human-murine mAb infliximab, initially approved by the FDA in 1999 to treat patients with Crohn’s disease who failed to respond to conventional therapy." (PMID 33540543, 2021). "Our results are in agreement with previous findings of elevated TNF-α expression in children with ASD and GI symptoms compared to non-inflamed controls that was similar to participants with Crohn’s disease." (PMID 30625189, 2019). "Here, we report the case of a patient with Crohn's disease who tested negative for HBsAg and positive for anti-HB core antibody (anti-HBc) and exhibited HBV reactivation during treatment with anti-TNF-α antibody (infliximab)." (PMID 25374717, 2013). "Vedolizumab therapy is indicated in the treatment of moderate or severe UC and Crohn’s disease worldwide, whereas in our country, vedolizumab is a treatment alternative in IBD patients refractory to anti-TNF treatments or who can not receive these treatments due to side effects." (PMID 35946879, 2022). "In addition, unlike anti-TNF antibodies, etanercept, which is not effective for the treatment of IBD, was correlated with the development of newly diagnosed ulcerative colitis and Crohn's disease in treated patients." (PMID 28083070, 2016). "However, the work presented here clearly demonstrates that TNF is not required for the development of IBD, at least in Il10−/− mice, a model with genetic, clinical, and histologic features that closely resemble human Crohn disease (CD)." (PMID 22848611, 2012).
periodontitis (1,128 papers, 2006 to 2026). An acute or chronic inflammatory process that affects the tissues that surround and support the teeth. "In conclusion, the current body of evidence suggests a potential association between periodontitis‐related inflammatory mediators, particularly TNF‐α, and elevated antibody responses to periodontal pathogens with AD progression." (PMID 41890452, 2026). "One of the key strengths of this study is its controlled evaluation of salivary and serum TMAO and TNF-α levels, which allowed for the isolation of periodontitis-associated changes from potential systemic confounders." (PMID 40131489, 2025). "Currently, SNP analysis and GWAS have detected genes polymorphisms associated with periodontitis in genes coding for pro-inflammatory cytokines, including IL-1, IL-6, TNF-α, and others involved in immune modulation and bone metabolism." (PMID 41300760, 2025). "This inflammatory state is exacerbated by elevated levels of pro-inflammatory markers, such as C-reactive protein (CRP), tumor necrosis factor-alpha (TNF-α), and interleukin-6 (IL-6), commonly associated with both periodontitis and cardiovascular diseases." (PMID 40066344, 2025). "Typically, IL-6 and TNF-α were positively associated with bone destruction and inflammation of periodontitis; blood CTXI and PINP serve as markers of bone resorption and bone formation, respectively." (PMID 41154794, 2025). "Taken together, these studies reinforce the notion that inflammatory arthritis and periodontitis share convergent pathogenic pathways involving TNF signaling, autophagy dysregulation, and Wnt-mediated bone remodeling." (PMID 41155385, 2025). "Biologic agents that neutralize specific cytokines like TNF-α or IL-6 have demonstrated efficacy in preclinical periodontitis models but carry the risk and cost associated with systemic immunosuppressive therapies." (PMID 41333482, 2025). "Persistent hyper-responsiveness of the stress system and the resulting excessive dampening of TNF-α responses are identified as a biological link between periodontitis and its associated risk factors and diseases." (PMID 41157245, 2025). "Due to differences in stress responsiveness, typical and atypical depression display opposite patterns in TNF-α, Th1, and Th17 responses and consequently in susceptibility to periodontitis." (PMID 41157245, 2025). "In the process of periodontitis, chemokines such as CXCL-8, CXCL-1, and CCL-5 and cytokines such as TNF-α, IL-1β, and IL-6 are present, due to the action of these multi-factors, it progresses to severe periodontitis with loss of periodontal support structures." (PMID 40733170, 2025). "Arg- and Lys-gingipain cysteine proteinases, which are virulence factors of Porphyromonas gingivalis (the causative agent of chronic periodontitis), stimulated TNF-α and IL-8 production by monocyte-derived macrophages, even without their enzymatic activity." (PMID 41019059, 2025). "In periodontitis, elevated TNF-α levels are strongly associated with inflammatory cell recruitment, extracellular matrix degradation, and alveolar bone resorption." (PMID 41124421, 2025). "Chronic periodontitis is known to contribute to systemic inflammation through the release of inflammatory mediators such as interleukin-6 (IL-6) and tumor necrosis factor-alpha (TNF-α), which are also implicated in prostate hyperplasia." (PMID 40004810, 2025). "These cytokines (such as TNF‐α, IL‐6, IL‐1β, and IL‐17) play a role in the bone destruction pathway of periodontitis and can cause bone resorption by regulating osteoclast formation." (PMID 40761494, 2025). "In response to elevated PGE, TNF-α, IL-1 and IL-6, periodontitis causes the liver to produce more CRP, especially in early pregnancy." (PMID 41394354, 2025). "Genetic polymorphisms mostly associated with periodontitis are those of genes coding for IL-1, IL-6, and TNF-α but, as already mentioned, the existing studies often gloss over inconsistent replication across ethnicities." (PMID 41300760, 2025).